SRD5A3 (steroid 5 alpha-reductase 3)
Diseases named in the same sentence as SRD5A3 in open-access papers (continued):
Sharing a sentence is not in itself a finding about the gene and the disease.
eczema (1 paper, 2020). "Among non-PMM2-CDG, skin allergies—particularly eczema—were the most reported, especially in ALG13-, SRD5A3- and PIGA-CDG." (PMID 32635232, 2020).
endometriosis (1 paper, 2023). The growth of functional endometrial tissue in anatomic sites outside the uterine body. "In addition, methylation at DNAm sites located near the KDR promoter on chromosome 4 are associated with endometriosis risk and expression of nearby SRD5A3 in blood." (PMID 37587191, 2023). "New endometriosis target genes detected include EEFSEC (eukaryotic elongation factor, selenocysteine-TRNA specific) on chromosome 3q21.3, SRD5A3 (steroid 5 α-reductase 3) on chromosome 4q12, ADK (adenosine kinase) on chromosome 10q22.2, and HOXC cluster on chromosome 12." (PMID 37587191, 2023).
ichthyosis (1 paper, 2021). Disorders of cornification that are characterized by visible scaling and/or hyperkeratosis of most or all of the skin. "It has been suggested that the accumulation of toxic sterol precursors could contribute to the cutaneous phenotype of SRD5A3-CDG, and could also explain ichthyosis being observed in DOLK-CDG." (PMID 34925443, 2021).
lymphoma (1 paper, 2025). A malignant (clonal) proliferation of B- lymphocytes or T- lymphocytes which involves the lymph nodes, bone marrow and/or extranodal sites. "We used The Human Protein Atlas (HPA) website to analyze the immunohistochemistry of SRD5A3 in tumor and normal tissues and found that the expression of SRD5A3 was higher in lymphoma, pancreatic cancer, and testicular cancer than in normal tissues." (PMID 40397909, 2025).
Nail dystrophy (1 paper, 2020). Onychodystrophy (nail dystrophy) refers to nail changes apart from changes of the color (nail dyschromia) and involves partial or complete disruption of the various keratinous layers of the nail plate. "Among the top associations, we recapitulated previously known, such as "SRD5A3—Abnormal full-field electroretinogram—recessive" and "GRHL2 –Nail dystrophy—recessive", and discovered one potentially novel, “RRAGA–Abnormality of the skin—dominant”." (PMID 32271766, 2020). "We applied Phenogenon to the Phenopolis exome dataset and were able to recapitulate known gene-phenotype relations, such as "SRD5A3—Abnormal full-field electroretinogram—recessive" and "GRHL2 –Nail dystrophy—recessive"." (PMID 32271766, 2020).
nonalcoholic fatty liver disease (1 paper, 2021). "Out of 482 positional candidate genes, 2 genes at Fmgq2 are found on metabolically relevant KEGG pathways: Srd5a3 (steroid hormone biosynthesis; mmu00140) and Cox7b2 (nonalcoholic fatty liver disease; mmu004932)." (PMID 33723359, 2021).
ovarian carcinoma (1 paper, 2025). A malignant neoplasm originating from the surface ovarian epithelium. "Our study found that SRD5A3 was highly expressed in most tumors, such as B-NHL, breast, liver, colorectal, and ovarian cancer, compared to normal control tissues, and that patients with SRD5A3 high expression had a poor OS." (PMID 40397909, 2025).
ovarian endometriosis (1 paper, 2016). A non-neoplastic disorder characterized by the growth of endometrial tissue in the ovaries. "SRD5A1 and SRD5A2 can convert both P to 5α-dihydroprogesterone in human ovarian endometriosis and T to 5α-dihydrotestosterone in human prostate, while the function of SRD5A3 in steroid metabolism is still unclear." (PMID 27149376, 2016).
primary immunodeficiency (1 paper, 2022). "Besides, one of the deceased patients, clinically diagnosed with a primary immunodeficiency (FJD_0728); carried a variant on the STAT3 gene (p.Asn175His), in addition to one pathogenic variant in the recessive SRD5A3 gene." (PMID 35725860, 2022).
retinitis pigmentosa (1 paper, 2014). Retinitis pigmentosa (RP) is an inherited retinal dystrophy leading to progressive loss of the photoreceptors and retinal pigment epithelium and resulting in blindness usually after several decades. "Retinitis pigmentosa might be a late sign in SRD5A3-CDG, and so is optic disc hypoplasia." (PMID 24433453, 2014).
Seizure (1 paper, 2022). A seizure is an intermittent abnormality of nervous system physiology characterized by a transient occurrence of signs and/or symptoms due to abnormal excessive or synchronous neuronal activity in the brain. "Seizures were present in most CDG patients, except in those with ALG12‐, DPM3‐, SRD5A3‐, and DPAGT‐CDG." (PMID 35279850, 2022).
seminoma (1 paper, 2025). A radiosensitive malignant germ cell tumor found in the testis (especially undescended), and extragonadal sites (anterior mediastinum and pineal gland). "The SRD5A3 gene coding for a testosterone—dihydro-testosterone (DHT) converting enzyme was the sole transcript upregulated in seminoma in both collectives." (PMID 40011822, 2025).
visual disorders (1 paper, 2016). "Eight positively selected genes within the tarsier lineage were implicated in several diseases associated with eye development and visual disorders (BBS2, BFSP2, IDUA, IL1A, IMPG1, RGR, SRD5A3 and TMC8)." (PMID 27708261, 2016).
tumor (9 papers, 2019 to 2025). "The expression of SRD5A1and SRD5A2 was negatively correlated with the HCC tumor stage, and the high expression of SRD5A3 was significantly positively associated with the high tumor stage." (PMID 36159555, 2022). "Studies have shown that SRD5A3 expression is usually higher in a variety of tumor tissues than in non-tumor tissues." (PMID 40397909, 2025). "In this study, the results of this study focused on the activity of testosterone-DHT transform and exhibited that the expression of SRD5A3 was overexpressed in the HCC tumor tissues." (PMID 36159555, 2022). "The transcriptional level of SRD5A3 was significantly upregulated in the tumor tissues relative to normal tissues." (PMID 36159555, 2022). "Recent research has demonstrated that high SRD5A3 expression facilitated tumor growth and led to poor survival in human hepatocellular cancer (HCC)." (PMID 34465365, 2021). "To visualize the localization of SRD5A3 protein in human tumor cells, we retrieved “SRD5A3” in the “Cell” retrieval tab in the HPA database." (PMID 34465365, 2021). "The differential expression of SRD5A3 in clinical tumor tissues and normal tissues was further verified in Gepia database and HPA database." (PMID 34465365, 2021). "The tumor growth curve, image and weight suggested that the down-regulation of SRD5A3 inhibited the growth of HCC." (PMID 33229626, 2020). "Our data displayed that the mRNA and protein expression of SRD5A3 were significantly increased in the tumor tissues of 36 HCC patients compared with the matched adjacent non-HCC liver tissues, which was consistent with the results in public datasets." (PMID 33229626, 2020). "Here, we found SRD5A3 was generally upregulated in HCC as well as many other malignant tumor tissues." (PMID 33229626, 2020). "Results showed that SRD5A3 knockdown could effectively inhibited the tumor growth of xenografts generated from T24R cells with or without CDDP treatment." (PMID 39680264, 2024). "Interestingly, the bioinformatics analysis showed that the level of SRD5A3 tended to be upregulated in more advanced tumor stages (stage 4 > stage 3 > stage 2 > stage 1) and positive node metastasis (N2 > N1 > N0)." (PMID 36159555, 2022). "Indeed, the main finding of our study is that SRD5A1 and SRD5A2 decreased and SRD5A3 significantly increased in HCC tumor tissues." (PMID 36159555, 2022). "In order to verify whether this high expression of SRD5A3 in HCC tumor tissues is a common phenomenon, seven HCC datasets including GSE22058, GSE25097, GSE36376, GSE63898, GSE64041, TCGA(LIHC), and GSE54236 were analyzed." (PMID 33229626, 2020). "Previous literature showed that SRD5A3 could promote tumor proliferation of HCC." (PMID 36159555, 2022). "Thus, the authors speculate that high expression of SRD5A3 may promote tumor cell proliferation and play an important role in the occurrence of the BC." (PMID 34465365, 2021). "In this study, we investigated the role of SRD5A3 and IGF2BP3 during bladder tumorigenesis and tumor cells resistant to CDDP." (PMID 39680264, 2024). "The results showed that CLDN9, AK4, PC, GPC1, and SRD5A3 were upregulated in EC tissues compared to in normal endometrium tissues, whereas B4GALT1, GMPPB, B4GALT4, and CHST6 were downregulated in tumor tissues." (PMID 31807118, 2019). "Nude mice implanted subcutaneously with CDDP-resistant T24 cells were injected intraperitoneally with CDDP (2 mg/kg) every 3 days for 35 days and the results demonstrated that SRD5A3 knockdown and IGF2BP3 knockdown effectively inhibited the tumor growth in subcutaneous implantation model." (PMID 39680264, 2024). "However, the shortcoming of this study is that we did not further validate the effect of SRD5A3 expression level on the growth of B-NHL by in vivo nude mice subcutaneous tumor formation experiments, which will be explored in the next step." (PMID 40397909, 2025). "The protein expression of SRD5A3 was not significantly different between tumor and normal tissues." (PMID 38248854, 2024).
tumor (continued). "In the current study, SRD5A3 expression in different cancers including HCC was analyzed by bioinformatics, and further verified with clinical specimens of HCC tumor (HCC) and corresponding adjacent non-HCC liver (peri-HCC)." (PMID 33229626, 2020). "Further analysis found that lentiviral-mediated SRD5A3 knockdown could overcome CDDP resistance in xenografts generated from T24R cells, as demonstrated by significantly reduced tumor growth in CDDP-treated xenografts than those without CDDP treatment." (PMID 39680264, 2024).
cancer (6 papers, 2020 to 2025). A tumor composed of atypical neoplastic, often pleomorphic cells that invade other tissues. "Since irreparable structural mutations in cells may result in cancer occurrence, we then determined the genetic alterations of SRD5A3, DOLK, SRD5A1, and HSD17B3 in BC." (PMID 34465365, 2021). "This suggests that SRD5A3 is pro-carcinogenic and involved in the proliferation of cancer cells, which is consistent with previous findings in other tumors." (PMID 40397909, 2025). "As an isoenzyme of SRD5A1 and SRD5A2, SRD5A3 has been discovered lately and it is demonstrated as an oncogene and confers a poor prognosis in several human cancers, such as breast cancer and hepatocellular carcinoma." (PMID 39680264, 2024). "These novel downstream targets would enrich our knowledge of the cancer-promoting mechanism of SRD5A3." (PMID 36159555, 2022). "Compared with the normal tissues, SRD5A3 mRNA was highly expressed in most of the cancers including BC." (PMID 34465365, 2021). "To investigate the expression of SRD5A3 in BC, we first visualized the mRNA expression of SRD5A3 in human cancer and normal specimens using the Oncomine database." (PMID 34465365, 2021). "We first employed the UALCAN web portal to explore the general expression of SRD5A3 in different cancers." (PMID 33229626, 2020). "Here, bioinformatics analysis was employed to explore the expression and prognostic significance of SRD5A3 in various cancers including HCC." (PMID 33229626, 2020). "Various cancers including HCC showed moderate to strong expression of SRD5A3 compared to their corresponding normal tissues." (PMID 33229626, 2020). "The expression of SRD5A3 tended to be increasingly upregulated in the advance cancer stage." (PMID 36159555, 2022). "We found that the elevated expression of SRD5A3 was common in many cancers with poor prognosis." (PMID 33229626, 2020). "SRD5A3 promotes B-NHL cell proliferation and attenuates cancer cell apoptosis by regulating the PI3K-AKT signaling pathway." (PMID 40397909, 2025). "Then, the correlation between SRD5A3 expression, clinical progression of HCC and survival prognosis of different cancer patients were studied." (PMID 33229626, 2020).
brain disease (1 paper, 2018). "Since we sought to examine the function of SRD5A3 in brain disease pathogenesis, we generated targeted conditional and null alleles of mouse Srd5a3, flanking exons 2 – 4 with loxP sequences." (PMID 30311906, 2018).
infection (1 paper, 2020). The state of being infected such as from the introduction of a foreign agent such as serum, vaccine, antigenic substance or organism. "Cell growth and differentiation (HRASLS2), transport (PNN, SLC4A4, and HBA1), metabolism (SRD5A3), and immune response (SSC4D) involved genes were highly regulated in the early HEV gt3 infection." (PMID 32877413, 2020).
retinal disorder (1 paper, 2020). Any disease or disorder of the retina. "Other examples include SRD5A3 –Abnormal full-field electroretinogram (HGF: 11.13) with recessive MOI (known to cause recessive congenital disorders of glycosylation, which may involve retinal disorders)." (PMID 32271766, 2020).
SRD5A3 also shares sentences with these, for which no sentence is quoted: Congenital Disorders of Glycosylation type 1Q (2 papers); glaucoma (2); Ataxia (1); Batten disease (1); benign prostatic hyperplasia (1); cervical cancer (1); Chorioretinal coloboma (1); cutis laxa (1); dilated cardiomyopathy (1); embryonal carcinoma (1); endometrial carcinoma (1); fructose intolerance (1); germ cell tumor (1); glioblastoma multiforme (1); glycosylation disorder (1); Hermansky-Pudlak syndrome 6 (1); Hypertension (1); Knobloch syndrome, type 1 (1); malaria (1); metabolic disorder (1); microphthalmia (1); mixed germ cell tumor (1); pancreatic cancer (1); sensorineural hearing loss (1); skin cutaneous melanoma (1); testicular cancer (1); thyroid carcinoma (1); uveal melanoma (1); yolk sac tumor (1).